BAP1 (BRCA1 associated deubiquitinase 1)
Diseases named in the same sentence as BAP1 in open-access papers (continued):
Sharing a sentence is not in itself a finding about the gene and the disease.
mesothelioma (continued). "To test if our observations hold true in human mesothelioma and whether these changes can be attributed to BAP1 only, we generated an inducible shRNA system (shCTRL or shBAP1) and used this to downregulate BAP1 in two human mesothelioma cell lines (MSTO and H2810)." (PMID 36657447, 2023). "In addition, recent clinical studies have indicated that PARP inhibition did not selectively target BAP1-deficient mesothelioma cells." (PMID 37009801, 2023). "Similarly, another two-cohort phase II trial of niraparib in pretreated patients with solid tumors (including mesothelioma) and BAP-1 or other DDR genes mutations failed to meet the pre-specified efficacy threshold of ORR (NCT03207347)." (PMID 37298116, 2023). "Two human families whose members showed a high incidence of mesothelioma were reported to carry germline BAP1 mutations and sporadic mesotheliomas in individuals without germline mutations showed somatic truncation mutations of BAP1 and aberrant BAP1 expression." (PMID 37009801, 2023). "Furthermore, up to 7% of mesothelioma patients may harbor germline variants in DNA repair complex genes such as BRCA1, BRIP1, CHEK2, SLX4, FLCN and BAP1 and these mutations may predispose one to the therapeutic effects of PARP inhibitors." (PMID 38136262, 2023). "However, these trials did not stratify patients on the basis of potential biomarkers; based on our results, we propose that the use of BAP1 as a biomarker could increase the efficacy of ZA in mesothelioma." (PMID 36657447, 2023). "In our case study, the mesothelioma did not have either the BAP1 or CDKN2A mutation." (PMID 35664766, 2022). "Furthermore, some cases of mesothelioma in-situ could be missed if the diagnosis is relied only in BAP1 lost expression, since other molecular can also be implicated." (PMID 35326567, 2022). "Interestingly, a recent study has revealed that BAP1 is not the only cancer-susceptibility-gene predisposing to mesothelioma." (PMID 34249695, 2021). "Interestingly, the frequency of EZH2, Survivin and BAP1 expression was similar in both low grade and high grade mesotheliomas, as well as in various growth patterns indicating that the combination of these markers is equally or similarly sensitive among all these morphological variants." (PMID 34257556, 2021). "There was a highly statistically significant association between positive Survivin IHC expression and BAP1 loss among mesothelioma cases, as 78% of positive Survivin cases had BAP1 loss compared to 23.1% only of negative Survivin IHC expression cases that manifested BAP1 loss IHC expression." (PMID 34257556, 2021). "Furthermore, mesothelioma cells lacking of BAP1, for acquired or inherited mutations, are resistant to gemcitabine-induced apoptosis." (PMID 31766522, 2019). "The gene encoding BRCA1-Associated Protein 1 (BAP1) serves as the most prevalent example of the impact of these high-throughput approaches, as it has been identified as one of the most frequently altered genes in mesothelioma through multiple molecular mechanisms." (PMID 30060501, 2018). "However, BAP1 mutations are also found in other types of tumors, thus its alteration is not exclusive to mesothelioma." (PMID 30060501, 2018). "These unusual findings—young age, family history, no history of exposure to asbestos made us suspect that the mesothelioma in our patient might have a genetic basis and that the patient might carry a germline BAP1 mutation." (PMID 30001711, 2018). "Similarly, if the family has cutaneous melanomas, uveal melanoma, renal clear call carcinoma, mesothelioma, or paraganglionoma, then a BAP1 test may be sufficient." (PMID 28283772, 2017). "Analysis of cancers in the pedigree of the proband carrying the S98R variant and in two other pedigrees carrying clear loss-of-function alleles showed the presence of BAP1-associated cancers such as renal cell carcinoma, mesothelioma and meningioma, but not uveal melanoma." (PMID 28062663, 2017).
mesothelioma (continued). "Deficient BAP1 is not specific to mesothelioma and is rather more often linked with other cancer types, and the biological significance is currently unknown." (PMID 23484132, 2013). "In this study, we investigated the context-dependent interplay between BAP1 and ubiquitin-specific protease 1 (USP1) in mesothelioma cells, focusing on their roles in regulating FANCD2, cell proliferation, and DNA damage responses." (PMID 42069682, 2026). "Homozygous deletion of BAP1 and cyclin-dependent kinase inhibitor 2A (CDKN2A/p16) by fluorescence in situ hybridisation (FISH) is highly specific for mesothelioma." (PMID 41147025, 2025). "In this study, we employed a quantitative proteomic mass spectrometry approach to assess alterations in protein expression following EZH2 inhibition in BAP1- and CDKN2A-proficient mesothelioma cells cultured as spheroids." (PMID 41226368, 2025). "In this cohort, BAP1 was altered in 44% of cases and TMB was consistently low in BAP1-altered tumors and wild-type mesotheliomas." (PMID 40361508, 2025). "One of seven patients with BAP1–TPDS developed additional malignancies (mesothelioma and cutaneous spindle cell melanoma) and died of complications of mesothelioma." (PMID 39268598, 2025). "We also followed 54 additional Bap1+/− FVB/N mice and 20 WT littermates, specifically seeking to expand our dataset to identify any further evidence of mesothelioma formation over the entire lifetime of animals in this genetic background." (PMID 40867321, 2025). "Currently, BAP1 determination is recommended by the ASCO and ESMO guidelines to establish the diagnosis of mesothelioma in situ in cases of suspected mesothelioma in patients with pleural effusion." (PMID 40361508, 2025). "Treating murine and human mesothelioma cell lines with concentrations that have no or little effect on cell viability as single agent led to an almost complete loss of cell survival when combined together, and this effect was exclusively observed in BAP1-deficient cell lines." (PMID 38054839, 2024). "Additionally, BAP1, enhancer of zeste 2 Polycomb progress complex 2 subunit, and S-methyl-5’-thioadenosine phosphorylase (MTAP) loss detected by immunohistochemistry, or CDKN2A (p16) homozygous deletion by FISH is used for differentiation between benign mesothelial proliferation and mesothelioma." (PMID 39006698, 2024). "This study investigated the role of IHC staining of BAP1, WT1, and calretinin and panels of their combinations in mesothelioma tumor tissue samples in predicting prognosis and response to chemotherapy in PM patients." (PMID 38280040, 2024). "In another study that screened for novel vulnerabilities in mesothelioma, inhibition of FGFR was shown to be effective against a subgroup of mesothelioma cell lines enriched for BAP1 alterations." (PMID 38054839, 2024). "(as IHC for BAP1 and MTAP) can be used to support the diagnosis of mesothelioma versus benign mesothelial proliferation." (PMID 39030439, 2024). "To test the efficacy of our drug combination in vivo, we transplanted the human mesothelioma cell lines NCI-H226 and its isogenic counterpart NCI-H226 + BAP1 WT into NOD-Scid IL2Rγnull mice." (PMID 38519707, 2024). "Taken together, all this data warrants further research into the indirect link between BAP1 and ATM and how this might affect DSB repair, and facilitates the investigation for clinical possibilities of this combination strategy against BAP1-deficient mesothelioma." (PMID 38519707, 2024). "Using two independent siRNAs, we found that BAP1 depletion led to a significant reduction in BRCA1 protein in the MSTO-211H and NCI-H2452 mesothelioma cell lines." (PMID 36550359, 2023). "Finally, by subjecting autochthonous Bap1-deficient mesothelioma mice or xenografts to mevalonate pathway inhibition (zoledronic acid) and PRC2 inhibition (tazemetostat), we demonstrate a potent anti-tumor effect, suggesting a targeted combination therapy for Bap1-deficient mesothelioma." (PMID 36657447, 2023).
mesothelioma (continued). "This suggests that while BAP1 and BRCA1 are both important for normal mitotic progression of mesothelioma cells, they are likely to have at least in part distinct functions." (PMID 36550359, 2023). "Next, we sought to identify key target genes of BAP1 commonly regulated by PRC2 repression in both mouse and human mesothelioma." (PMID 36657447, 2023). "The role of BAP-1 and MTAP in the diagnosis of mesothelioma in situ and in the prognosis of malignant pleural mesothelioma is the main topic of recent studies." (PMID 36553016, 2022). "Meanwhile, we demonstrated the increased expression of seven MPM biomarkers including BAP1, EMA, CD141, WT1, D2-40, Calretinin and CK6 in 3D cultured patient mesothelioma cancer cells compared to its 2D counterparts." (PMID 36091141, 2022). "After excluding benign renal neoplasia (such as oncocytoma and angiomyolipoma), alterations of BAP1, FLCN, and MITF were identified in 5 of 81 patients (6.2%) with melanoma and/or mesothelioma and renal neoplasia." (PMID 34767027, 2021). "This recapitulates the histological features and gene profile observed in human patients carrying combined BAP1, NF2 and CDKN2A alterations, indicating that the combined deletion of these tumor-suppressor genes creates a mesothelioma-specific microenvironment." (PMID 34830817, 2021). "Clonal positive selection (dN/dS>1) involved five tumour suppressors NF2, BAP1, SETD2 which were independently validated in the mesothelioma TCGA7, FBXW7 and PRELID1." (PMID 33741915, 2021). "Thus, alterations of the ubiquitination event may be one of the key factors driving mesothelioma, and this is emphasized by the fact that another tumor suppressor frequently mutated in MPM, BRCA1-associated protein-1 (BAP1), also functions as a nuclear deubiquitinating enzyme." (PMID 33233664, 2020). "The aim of this study was to assess the functional relationship between BAP1 and BRCA1 and examine their role in genome stability in mesothelioma cells." (PMID 30405205, 2018). "We report here an unbiased DUB siRNA screen that has identified BAP1 as a regulator of HDAC2 expression in lung cancer and mesothelioma cells." (PMID 25970771, 2015). "Together, these findings identify USP1 as a context-dependent therapeutic vulnerability in BAP1-deficient mesothelioma and support a working model in which USP1-dependent maintenance of FANCD2 function becomes critical in the absence of functional BAP1." (PMID 42069682, 2026). "Our analysis of the expanded set of mice from several different genetic backgrounds demonstrates that germline Bap1 heterozygous mice do not have a statistically significantly higher incidence of spontaneous mesotheliomas compared to WT mice." (PMID 40867321, 2025). "Conversely, a single-institution study on mesothelioma indicated that BAP1 does not have an impact on the response to immune checkpoint inhibitors or on disease progression." (PMID 39939955, 2025). "No mesotheliomas were found in 43 WT mice, although the difference in mesothelioma incidence between Bap1-mutant and WT groups was not statistically significant (p > 0.05, Fisher’s exact test)." (PMID 40867321, 2025). "BAP1 nuclear expression was retained, and fluorescence in situ hybridization (FISH) for p16 (CDKN2A) was negative for homozygous deletion, distinguishing the lesion from mesothelioma." (PMID 40330366, 2025). "The most commonly inactivated tumor suppressor genes in mesothelioma are NF2, BAP1, and CDKN2A." (PMID 40362535, 2025). "To address this issue, we evaluated spontaneous mesothelioma development over the lifetime of a large cohort of Bap1-mutant mice and non-mutant, wild-type littermates across several genetic backgrounds." (PMID 40867321, 2025).
mesothelioma (continued). "Spontaneous mesotheliomas were observed in two Bap1-mutant mice in an FVB/N background but were not seen in any Bap1-mutant mice in C57BL/6 or Sv129 backgrounds." (PMID 40867321, 2025). "The mesothelioma cells were BAP1-positive, in line with expectations for the sarcomatoid subtype since only 20% are BAP1 negative (Righiet al., 2016)." (PMID 40568242, 2025). "Since our original report, however, no additional mesotheliomas have been identified in 54 additional Bap1+/− FVB/N mice followed to their end of life." (PMID 40867321, 2025). "Rucaparib demonstrated only modest antitumor efficacy in patients with mesothelioma, and losses of BAP1 or BRCA1 were not predictive of response to rucaparib." (PMID 40361508, 2025). "The analyses did not detect a significant difference in the probabilities of mesothelioma occurrence between Bap1-mutant and wild-type mice." (PMID 40867321, 2025). "TRAF7 was enriched in WDPMT, while common mesothelioma alterations (BAP1, NF2, CDKN2, and SETD2) were absent." (PMID 39167353, 2024). "BAP1 signal localized mainly in the nucleus, and its expression was significantly higher in CDDP- and Pt(IV)Ac-POA-treated mesothelioma cells at 12 h compared to untreated mesothelioma cells (p < 0.0001)." (PMID 39204360, 2024). "Taken together, these results suggest that BAP1 contributes to regulation of microtubule length and spindle pole attachment during mitosis in mesothelioma cells in a manner that is independent of BRCA1." (PMID 36550359, 2023). "Further, we validated these observations in two additional BAP1-negative mesothelioma cell lines and consistently observed that genes belonging to cholesterol metabolism are upregulated upon treatment with an EZH2 inhibitor." (PMID 36657447, 2023). "We then analysed BAP1 and BRCA1 protein expression in three primary mesothelioma cell lines." (PMID 36550359, 2023). "Similar triple-knockout mouse models also confirmed that, although Bap1 deletion alone did not induce mesothelioma, Bap1 deletion dramatically accelerated mesothelioma development with the combined disruption of Nf2 and Cdkn2ab." (PMID 37180489, 2023). "As expected, high tumor cell MSLN expression coincided with diffuse D2-40 expression by mesothelioma cells because both proteins are located in the cellular membrane, while nuclear expression of WT-1 and BAP-1 showed non-specificity with MSLN." (PMID 37901248, 2023). "Absence of typical mesothelioma NF2 and BAP1 driver events argued against a mesothelioma, and subsequent negative H3K27me3 staining further strengthened the diagnosis of sarcoma." (PMID 35053600, 2022). "Several studies have shown that many—but not all—mesothelioma patients with germline BAP1-TPDS are characterized by prolonged survival compared to wild-type (wt) BAP1 patients." (PMID 35885614, 2022). "Recently, loss of expression of BRCA1 associated protein 1 (BAP1) and/or methylthioadenosine phosphorylase (mTAP) has been described in various carcinomas and mesotheliomas but not in reactive mesothelial proliferation." (PMID 35565429, 2022). "Further functional evaluation in BAP1 wild-type, BAP1 knocked down, and BAP1 noncatalytically expressing NCI-H226 mesothelioma cells indicate that BAP1 enzymatic activity was a requisite to maintain these proteomic and genomic phenotypes." (PMID 31781477, 2019).
mesothelioma (continued). "The human mesothelioma cell lines MSTO-211H (BAP1 positive) and NCI-H28 (BAP1 negative) were used as controls for BAP1 immunoreactivity, and β-actin was used as a loading control." (PMID 30060843, 2018). "In addition, we validated the statistical deregulation of 66 genes out of the selected 117, among which there were several well-known mesothelioma genes, such as MSLN, BAP1, and NF2." (PMID 27835874, 2017). "Functional assessments in BAP1 inactivated, BAP1 wild-type and BAP1 catalytically dead-expressing NCI-H226 and QR mesothelioma cell lines confirmed alteration of these pathways and demonstrated that BAP1 deubiquitinase activity was mandatory to maintain these phenotypes." (PMID 29069806, 2017). "An enhanced sensitivity to EZH2 inhibition was reported in mesothelioma cells lacking BAP1, and related to enhanced expression of SETD8, a methyl transferase that decreased EZH2 expression and further restricted cell proliferation in these cells." (PMID 28122578, 2017). "Immunoblotting confirmed that BAP1 protein was expressed in the three wild-type lines, and was absent in the BAP1 null mesothelioma cell lines." (PMID 25970771, 2015). "Thus the expression of the other genes commonly deleted in human mesothelioma, NF2, BAP1 and LATS2 was investigated." (PMID 26680231, 2015). "However, no obvious changes in expression of other genes frequently altered in human mesothelioma such as NF2 and BAP1 was observed in MexTAg tumours." (PMID 26680231, 2015). "For western blot analysis, we used the mesothelioma cell lines NCI-H28 (harboring a BAP1 nonsense mutation) and NCI-H2052 (wild type for BAP1) as positive and negative controls, respectively, for the presence of a BAP1 protein." (PMID 25952750, 2015). "We recommend that testing of BAP1 should not be conducted routinely in CM families but reserved for families with CM and UM, or mesothelioma, and possibly also families with the occurrence of RCC." (PMID 25803691, 2015). "In recent findings, BAP1 has also emerged as both somatic and germline targets in mesotheliomas though mesotheliomas were not reported by any of our carriers." (PMID 22545102, 2012). "This suggests that the observed data are not highly unusual under the null hypothesis, further supporting the conclusion that there is no strong evidence for an increased mesothelioma incidence in Bap1-mutant compared to WT mice." (PMID 40867321, 2025). "No mesotheliomas were observed in control unexposed Bap1-mutant or WT mice." (PMID 40867321, 2025). "Similarly, no spontaneous mesotheliomas were observed in heterozygous Bap1+/− mice in either 129/Sv or C57BL/6 backgrounds." (PMID 40867321, 2025). "Extensive analyses were performed using published (historical) lifetime data from wild-type mice and multiple statistical frameworks to determine whether mesothelioma incidence in Bap1-mutant mice differs from that of non-mutant mice." (PMID 40867321, 2025). "Likewise, no spontaneous mesotheliomas were identified in Genentech’s Bap1+/− or Bap1+/+ (WT) mice in a C57BL/6 background." (PMID 40867321, 2025). "Based on these analyses, we report that there is insufficient evidence to support a statistically significant difference in the incidence of spontaneous mesotheliomas between germline Bap1 heterozygous mice and WT mice in the absence of environmental carcinogenic exposure." (PMID 40867321, 2025). "In addition, no spontaneous mesotheliomas were seen in germline Bap1+/− mice in a C57BL/6 background obtained from Genentech." (PMID 40867321, 2025). "The importance of these findings, besides stratification according to survival, is that there is an apparent subgroup of BAP1 loss patients that will not respond to chemotherapy at all, given that both WT1 and calretinin both are negative, a “triple-negative” subtype of mesothelioma (5/5 patients)." (PMID 38280040, 2024).